IL10 (interleukin 10)
Diseases named in the same sentence as IL10 in open-access papers (continued):
Sharing a sentence is not in itself a finding about the gene and the disease.
tumor (continued). "M2-like TAM have high levels of mannose receptor-1 (MRC1/CD206), arginase-1 (Arg1), IL-10 and chemokines CCL22 and CCL17, whereas anti-tumor M1-like TAM express high interferon (IFN)γ and IL-1α/β levels; TNFα marks both M1- and M2-polarized TAM." (PMID 24317954, 2013). "The production of the IL-2, IL-10, IFN-γ and TGF-β cytokines was observed in the B16F10 cells and also detected in the tumoral microenvironment during tumor growth (7, 14 and 21 days)." (PMID 24179494, 2013). "Tumor-derived factors such as TGF-β, VEGF, IL-10, and PGE2 and other factors such as gangliosides and lactate have been verified to be able to regulate differentiation and function of dendritic cells (DC) and T cells." (PMID 24129179, 2013). "Many tumor cells secrete multiple immune-suppressive factors such as transforming growth factor β1 (TGF-β1), vascular endothelial growth factor (VEGF), and IL-10." (PMID 23717436, 2013). "Tumor-derived soluble factors, such as VEGF, SDF-1, IL-10, and TGF-β, have been acknowledged to be responsible for expansion of iTreg in tumor-bearing hosts." (PMID 23898333, 2013). "Next, we demonstrated that the production of active TGF-β1, IL-10 and VEGR from tumor cells was significantly inhibited by a simple treatment of pharmaceutical grade ethanol without the down-regulation of MHC class I and the MUC1 tumor-associated antigen." (PMID 23717436, 2013). "Analysis of tumor-infiltrating CD45+ leukocytes showed consistent Lov-mediated upregulation of IFNγ and IL-1β (M1 markers) and downmodulation of IL-10, CD206 and CCL22 (M2 markers)." (PMID 24317954, 2013). "We further investigated both CD4 and CD8 T cells from the spleen for their ability to secrete antigen-induced inhibitory cytokines such as IL10 and TGF-β in C3 tumor challenge model." (PMID 23533812, 2013). "Studies have shown tumor escape mechanisms in STAT-1−/− mice, and STAT-3 signaling was identified in the inhibitory effects of IL-10 on DC maturation and migration, and impairment of CD4+ T-cell function." (PMID 24216992, 2013). "Another well established target of miR-21 is the tumor suppressor PDCD4, a proinflammatory protein that promotes activation of the transcription factor NF-κB and suppresses interleukin 10 (IL-10)." (PMID 23506673, 2013). "It has been thoroughly demonstrated that during the tumor development, tumor microenvironment (such as the secretion of TGF-β and IL-10) can educate T cells into regulatory T cells (Treg) or more and more T cells became ignorant." (PMID 24078089, 2013). "Several tumor-derived factors such as IDO/TDO, CCL-2, VEGF, TGF-β, M-CSF, GM-CSF, IL-6, and IL-10 have been reported to negatively impact DC functions." (PMID 24339825, 2013). "In this study, we found the combination therapy decreased the frequency of Tregs, and increased CD8+ T cells and CD4+ T cells at tumor sites, with increased levels of IL-12 and IFN-γ and decreased IL-10 and TGF-β1." (PMID 24304581, 2013). "Tumor RTL and T/N RTL ratio correlated positively with three of the cytokines (IL-7, IL-8 and IL-10), whereas TA correlated inversely with IL-7 and IL-8." (PMID 23383336, 2013). "On the other hand, the tumor microenvironment includes a number of chemoattractants, such as IL-4, IL-13, TGF-β, and IL-10, all of which lead to the adoption of an M2 phenotype." (PMID 22778768, 2012). "For example, the differentiation and activation of dendritic cells, which are the key initiators of adaptive immune responses, are inhibited by signals (such as IL-10 and VEGF) present in the tumour microenvironment." (PMID 22778767, 2012). "Tumor cells, stromal cells like fibroblasts, and tumor-infiltrating immune cells and/or their secreted products, like VEGF, M-CSF, IL-6, IL-10, and TGF-β are also responsible for systemic and local DC defects." (PMID 23217146, 2012). "Many potential mediators of the immunologically hostile microenvironment have been proposed including tumour-derived TGFβ, Prostaglandin E2 (PGE2) and Interleukin-10 (IL-10)." (PMID 22666318, 2012).
tumor (continued). "The same expression pattern, that is, strong TGF-β1 expression but only moderate IL-10 expression, was present in LLA-TG-3 tumor cell lines." (PMID 22674057, 2012). "We used a multistage model of SCC to examine the involvement of elastase (ELA), myeloperoxidase (MPO), nitric oxide (NO), cytokines (IL-6, IL-10, IL-13, IL-17, TGF-β and TNF-α), and neutrophils and macrophages in tumour development." (PMID 23176085, 2012). "IL-10, TGF-β, and VEGF all have been identified as key factors that mediate the inhibitory action of the tumor microenvironment." (PMID 22592077, 2012). "Two of the key molecules mediating the inflammatory processes in tumour promotion are cytokines tumour necrosis factor-α (TNF-a), and IL10." (PMID 22520842, 2012). "An important mechanism by which IL-10, TGF-β, and VEGF counteract the development of an anti-tumor immune response is through inhibition of DC differentiation, maturation, trafficking, and antigen presentation." (PMID 22592077, 2012). "Very recently, it was observed that MCPyV-specific T-helper cells secrete the IL13, IL10 cytokines, and IFN-gamma, that have a strong tumour-suppressing and antiviral functions." (PMID 22489251, 2012). "Meanwhile, IL-10 directly activates and expands the antigen-specific IFN-γ-producing effector CD8 T cell pool inside the tumor, resulting in higher IFN-γ levels which trigger the increased expression of intratumoral antigen presenting molecules." (PMID 22827934, 2012). "Other reports have also shown that increased anti-inflammatory cytokines like IL-10 and TGF-β can help Tregs suppress the function of antigen-presenting cells and arrest the activation of effector T lymphocytes during tumor progression." (PMID 23082146, 2012). "The tumor microenvironment has immune suppressive mediators such as PGE2, TGF-β, IL-10, VEGF, GM-CSF, IL-6, S100A8/A9 and SCF that recruit and/or activate MDSC." (PMID 22815789, 2012). "IL-10, an important cytokine in the tumor microenvironment, is expressed by TAMs, CD8+ T-cells, and tumor cells." (PMID 22778768, 2012). "Immunosuppressive cytokines and growth factors known to be secreted directly by tumor cells include IL6, IL10, TGF-β, and VEGF." (PMID 22312408, 2012). "A variety of tumor-derived factors contribute to the emergence of complex local and regional immunosuppressive networks, including VEGF, IL-10, TGF-β, and PGE-2." (PMID 22030012, 2011). "Observations to date implicate the HCMV IE1, gB, IL-10 and US28 gene products as tumor promoters in gliomagenesis." (PMID 22030012, 2011). "Our data indicated that in tumor-bearing mice, GP significantly decreased IL-10 and TGF-β production in peripheral blood and IL-10 mRNA expression in the lymph nodes." (PMID 21963624, 2011). "Pre-treatment of monocyte derived dendritic cells with this tumour conditioned media inhibited the up-regulation of CD86, CD83, CD54 and HLA-DR in response to LPS, enhancing IL-10 while reducing IL-12p70 secretion." (PMID 22125641, 2011). "In addition to that elevated expression of anti-inflammatory cytokine (IL-10) was observed in the EBV+ (positive) samples in comparison with EBV- samples (undetectable or negligibly low levels of expression) which indicate its relevance with viral persistence in EBV transformed tumour cells." (PMID 21791113, 2011). "M1 cells, when stimulated by LPS or IFNγ/TNF induce production of IL-1, TNF, IL-6, IL-23, IL-12, and IL-10, which can be involved in a DTH response, type 1 inflammation, Th1 responses, promoting anti-tumor activity." (PMID 21281484, 2011). "We demonstrate that Tumour Conditioned Media (TCM) from cultured colorectal cancer tumours significantly inhibited LPS induced DC maturation, markedly increasing IL-10 while decreasing IL-12p70 secretion in response to LPS." (PMID 22125641, 2011).
tumor (continued). "Moreover, IFN-γ can antagonize the production of immunosuppressive cytokines such as TGF-β and IL-10 which can promote the development of otherwise highly immunogenic tumors, improves the establishment of an effective antitumor memory immune response, and thus controls ongoing tumor growth." (PMID 21943203, 2011). "When pro-tumor growth mediators such as IL-6, IL-10, MMP-9, and VEGF are the primary secreted factors from TAMs, then tumor angiogenesis, enhanced cell motility, and increased tumor cell invasion are facilitated." (PMID 21385454, 2011). "M2-type macrophages from experimental tumors and various types of cancers express arginase-1 (Arg1), IL-10 and transforming growth factor beta 1 (TGF-β1), support tumor invasion, angiogenesis and matrix remodelling." (PMID 21901144, 2011). "There is ongoing pre-clinical work supporting the neutralization of suppressive cytokines, such as IL-10 and TGF-β in promoting anti-tumor immunity." (PMID 24213115, 2011). "DCs maturation was evaluated by IL-12/IL-10 production and CD80/CD86 expression after co-culture with tumor cells treated with different HIFU." (PMID 20105334, 2010). "Compared to the IL-10 expression in the total tumor population, CD45+ cells produced 700 times more IL-10 mRNA than CD45- cells." (PMID 20525400, 2010). "Expression of cytokines IL-10, TGF-β and TNF-α were increased during tumor growth whereas IFN-γ showed a decrease of the expression from day 10 on following an initial increase." (PMID 20205946, 2010). "In contrast with the induction of Foxp3+ Treg cells in the periphery, there is evidence that in the tumor microenvironment, STAT3 signaling through IL-23R expression increases Foxp3 and IL-10 expression by Treg cells." (PMID 20732640, 2010). "Taken together, our results show that at the outset of tumor progression, BTM group animals produced large quantities of TNF-α and IFN-γ and little IL-10, and they showed fungal clearance." (PMID 19534779, 2009). "Both tumor cell lines successfully inhibited IFN-γ and TNF-α secretion and promoted IL-10 secretion, with the latter, primarily produced by the monocytes, as determined using immunofluorescence and flow cytometry." (PMID 19718269, 2009). "Our results showed that at the outset of tumor progression, the mice produced more IFN-γ and TNF-α and less IL-10; they also exhibited fungal clearance." (PMID 19534779, 2009). "The immune-inhibitory mechanisms developed by tumor cells, such as overproduction of immunosuppressive cytokines (TGF-β and IL-10) or induction of Treg cells, are important obstacles that a successful cancer immunotherapy strategy has to face." (PMID 19272130, 2009). "The first, described previously, is mediated by tumor-derived factors such as VEGF and IL-10, that promote the generation of immature DCs that lack the T cell stimulatory activity characteristic of mature DCs." (PMID 19718269, 2009). "During the course of tumor development, the tumor evades the immune system through the secretion of various factors such as VEGF, IL-10 and PGE2 that have been shown to inactivate the immune system." (PMID 18533025, 2008). "These cells, isolated from draining lymph nodes of patients with pancreas orbreast cancer secrete IL-10 and TGF-β, prevent activated CD4+ CD25− and CD8+ effector T cells, and suppress tumor-specific immune response." (PMID 19009040, 2008). "On the other hand, IL-2, IL-6, IL-8, IL-10, IFN-γ, MCP-1, MIP-1β, TNF-α and, to a lesser extent, IL-1β and IL-13 were significantly overexpressed in ER-negative tumours compared with ER-positive ones, with the greatest differences observed for IL-8 and MCP-1." (PMID 17261184, 2007). "The cytokines most often detected in serum and ascites of patients with EOC include TNFα, IL-10, IL-6, CSF1 (MCSF), IL-1, and TGFβ isotypes, all of which can be produced by activated MA or by the tumor cells." (PMID 16824216, 2006).
tumor (continued). "Tumors can suppress CD4+ T cell activity and CTL tumor lysis directly through secretion of immunosuppressive factors including TGF-β1 but also PGE-2, and IL-10." (PMID 16045800, 2005). "The expression of cytokines such as IL-2, IL-6 and IL-10 in NPC has been studied mainly on tumor biopsies using immunohistochemical and molecular techniques." (PMID 15450122, 2004). "In this report, we investigated the ability of peripheral (PBL) and tumor- infiltrating (TIL) lymphocytes of undifferentiated NPC patients to produce in vitro three interleukins (IL-2, IL-6, IL-10) and three immunoglobulin isotypes (IgM, IgG, IgA)." (PMID 15450122, 2004). "In this context, it is noteworthy that COX-2 can up-regulate the immunosuppressive cytokine IL10, while reducing the production of IL12, which is critical for cell mediated anti-tumour immunity." (PMID 12402155, 2002). "Furthermore, GABA secreted by tumor or immune cells, particularly B cells, directly suppresses CD8+ T cell activity while steering monocyte differentiation toward anti‐inflammatory IL‐10+ macrophages, thus constraining cytotoxic and antitumor T cell responses." (PMID 41583906, 2026). "It has been well recognized that M-MDSCs and PMN-MDSCs both express multiple immunosuppressive signals within the tumor microenvironment, including arginase-1 (ARG1), inducible nitric oxide synthase (iNOS), programmed death-ligand 1 (PD-L1), and interleukin 10 (IL-10)." (PMID 41614948, 2026). "Tegs secrete IL-10 and TGF-β in the tumor, reinforcing M2 polarization of TAMs." (PMID 41597210, 2026). "The microbiome also modulates the Th17/Treg balance within the TME, influencing cytokine production that can either promote inflammation and anti-tumor immunity (e.g., IFN-γ, IL-17) or suppress immune responses (e.g., IL-10 from Tregs or regulatory Th17 cells)." (PMID 41486167, 2026). "IL-4 and IL-10 suppress antitumor adaptive immunity and promote HNSCC tumor growth." (PMID 41431358, 2026). "B cells can induce the formation of an immunosuppressive environment and promote angiogenesis by secreting cytokines such as IL‐10 and TGF‐β, while simultaneously suppressing the activity of T cells and NK cells, thereby driving tumor invasion within brain tissue." (PMID 41583906, 2026). "Pathophysiologically, CAR T‐cell recognition of tumor cells induces a burst of IFN‐γ and other effector cytokines that activate monocytes/macrophages, which then amplify the inflammatory cascade through secretion of IL‐6, IL‐1, IL‐10, and TNF." (PMID 41207679, 2026). "Notably, IL-1β, NOS2, COX-2, IL-10, and VEGF were consistently upregulated in tumor tissues of ETBC mice." (PMID 41939865, 2026). "In other cases, B cells may acquire a regulatory phenotype secreting IL-10 and TGF-β, which ultimately promote tumor aggression and immunosuppression in macrophages, neutrophils, and cytotoxic T cells." (PMID 39941775, 2025). "It has been demonstrated that tumor cells in the sentinel lymph node (SLN) secrete immunosuppressive cytokines (e.g., IL-10, TGF-β), which impair Langerhans cell function by downregulating the expression of costimulatory molecules CD80/CD86 and maturation markers (CD83)." (PMID 40725022, 2025). "Metformin (Met) reduces tumor-infiltrating Treg (Ti-Treg), especially in the terminally differentiated CD103+KLRG1+ population, and also reduces expression of immune suppressive effector molecules such as CTLA4 and IL-10." (PMID 41246345, 2025). "GBM is characterized by extensive infiltration of tumor-associated macrophages and microglia that frequently acquire an M2-like, immunosuppressive phenotype; these cells secrete cytokines such as IL-10 and TGF-β, inhibit cytotoxic T-cell activity, and promote tumor progression." (PMID 41301809, 2025). "Moreover, gastric cancer-derived EVs stimulate TAMs to secrete excessive IL-10, which serves as an inhibitory cytokine to impair CD8 + T function, thereby sustaining tumor growth." (PMID 40908470, 2025).
tumor (continued). "Tregs suppress effector T cell activity through various mechanisms, including the secretion of immunosuppressive cytokines (e.g., IL-10 and TGF-β) and the expression of immune checkpoint proteins (e.g., CTLA-4 and PD-1), thereby allowing tumor cells to evade immune surveillance." (PMID 41020815, 2025). "In addition to TNF-α (Padj < 0.001), tumor tissue from the TNF-α High group secreted significantly higher levels of MIF and IL-10 (both Padj < 0.05)." (PMID 39923035, 2025). "This miRNA enhances IL-10 secretion in gastric cancer cells by targeting the RB1/NF-κBp65 pathway, thereby facilitating Treg differentiation, regulating EMT, and remodeling the tumor immune microenvironment." (PMID 41229433, 2025). "Additionally, AS-IV downregulated anti-inflammatory cytokines such as TGF-β, IL-10, and VEGF-A while upregulating pro-inflammatory cytokines including IFN-γ, IL-12, and TNF-α, thereby fostering a more immunologically active tumor milieu." (PMID 40417220, 2025). "The cervical region contains not only superficial subcutaneous fat but also metabolically active brown adipose tissue, which may influence systemic inflammation and the tumor microenvironment (TME) via secretion of adiponectin, IL-10, and FGF21." (PMID 40731020, 2025). "Puerarin greatly enhances the expression of anti-tumor cytokines IFN-γ, TNF-α, and IL-12, while diminishing the levels of anti-inflammatory cytokines IL-10, IL-4, and TGF-β, thereby inhibiting the polarization of M2-TAM and promoting the polarization of M1-TAM." (PMID 40370720, 2025). "In contrast, M2-type microglia are activated by anti-inflammatory cytokines, such as IL-4, IL-10, IL-13, and TGF-β, and secrete anti-inflammatory and immunosuppressive factors such as CCL5, TGF-β and MMPs, which facilitate tumor cell proliferation and the establishment of brain metastases." (PMID 41219968, 2025). "Selective depletion of interleukin-10-expressing (IL-10+) Treg cells promoted tumor growth by lifting the restraint on IL-17 production from effector CD4+ T cells, thereby directly stimulating tumor cell proliferation; depletion of IL-10- Treg cells led to pronounced tumor regression." (PMID 41401810, 2025). "The immune suppression in TME arises from several mechanisms: 1) Tumor and stromal cells produce factors like transforming growth factor-β (TGF-β), prostaglandin E2 (PGE2), and interleukin-10 (IL-10), which impair the maturation of antigen-presenting cells (APCs) in the TME." (PMID 40352942, 2025). "Concurrently, tolerogenic DCs—modulated by IL-10 and TGF-β—fail to present tumor antigens effectively and may promote the expansion of Tregs." (PMID 40940834, 2025). "Additionally, LINC00958-containing exosomes induce M2 macrophage polarization, a tumor-supportive immune phenotype characterized by markers like CD206 and the expression of immunosuppressive genes such as IL-10 and Arg-1." (PMID 40330466, 2025). "Many of them can act as factors enhancing tumor progression, activating angiogenesis (IL-1ß, TNF-α), tumor cell migration (IL-1ß, IL-6, IL-8), epithelial cell metaplasia (IL-6), and some stimulators and products of T regs (IL-10)." (PMID 40806737, 2025). "An IL-10-Fc fusion protein acts through IL-10 receptors on T cells to specifically enhance OXPHOS, proliferation and cytotoxicity in this subset, thereby reversing exhaustion and enhancing anti-tumor response." (PMID 41268548, 2025). "Within the tumor microenvironment, TAMs facilitate tumor progression by stimulating angiogenesis, remodeling the extracellular matrix, and suppressing immune responses through factors including VEGF, MMPs, PD-L1, and IL-10." (PMID 40807088, 2025). "Moreover, Tregs recruited and educated by the tumor infiltrate draining lymph nodes and suppress NK cell activity, reducing their ability to eliminate disseminated tumor cells through TGF-β and IL-10 secretion and enhanced PD-L1 expression." (PMID 40211394, 2025).